FABP7 (fatty acid binding protein 7)
Description:
B-FABP could be involved in the transport of a so far unknown hydrophobic ligand with potential morphogenic activity during CNS development. It is required for the establishment of the radial glial fiber system in developing brain, a system that is necessary for the migration of immature neurons to establish cortical layers (By similarity).
Synonyms: BLBP; B-FABP; FABPB; MRG
Tractability: Small molecule: a structure with a bound ligand is known; a high-quality ligand is known; it has a binding pocket of medium quality. PROTAC: its protein half-life has been measured; a small molecule that binds it is known.
Target class: Fatty acid binding protein family; Auxiliary transport protein
Gene: Protein-coding gene on chromosome 6 (122,779,716 to 122,784,074, forward strand). Ensembl gene ENSG00000164434.
Subcellular location: Cytoplasm
Subcellular location (Human Protein Atlas): Nucleoplasm; Cytosol; Golgi apparatus
Pathways (Reactome):
Metabolism: Triglyceride catabolism
Signal Transduction: NOTCH3 Intracellular Domain Regulates Transcription
Gene Ontology:
Molecular function: protein binding; fatty acid binding; lipid binding; lipid transporter activity
Biological process: fatty acid transport; negative regulation of cell population proliferation; nervous system development; triglyceride catabolic process; epithelial cell proliferation
Cellular component: cytosol; nucleus; cytoplasm
Genetic constraint (gnomAD): Loss-of-function variants: 13 observed, 15.15 expected, observed/expected ratio (o/e) 0.86, 90% interval 0.56 to 1.36. The upper end of that interval is the gene's LOEUF score, 1.36, which puts it in group 5 of 6, group 1 being the genes least tolerant of losing a copy. Missense variants: 149 observed, 165.27 expected, observed/expected ratio (o/e) 0.9, 90% interval 0.79 to 1.03. Synonymous variants: 49 observed, 54.15 expected, observed/expected ratio (o/e) 0.9, 90% interval 0.72 to 1.15.
Homologues: Orthologues: macaque FABP7 (98% identical), rabbit FABP7 (92% identical), chimpanzee FABP7 (89% identical), guinea pig FABP7 (87% identical), pig FABP7 (87% identical), zebrafish fabp7a (83% identical), rat Fabp7 (80% identical), mouse Fabp7 (79% identical), zebrafish fabp7b (79% identical), Caenorhabditis elegans lbp-7 (39% identical), Caenorhabditis elegans lbp-8 (33% identical). Paralogues in human: FABP3 (67% identical), PMP2 (59% identical), FABP4 (57% identical), FABP9 (53% identical), FABP12 (48% identical), FABP5 (45% identical), CRABP2 (40% identical), RBP1 (39% identical), CRABP1 (39% identical), RBP2 (39% identical), RBP7 (38% identical), FABP2 (30% identical), and 3 more.
Diseases named in the same sentence as FABP7 in open-access papers:
FABP7 is named in the same sentence as 135 diseases in open-access papers, as found by Europe PMC text mining. Sharing a sentence is not in itself a finding about the gene and the disease. The quoted sentences say what the papers report.
breast cancer (51 papers, 2006 to 2026). A primary or metastatic malignant neoplasm involving the breast. "For example, nuclear localization of FABP7 in breast cancer is associated with longer disease-free survival." (PMID 40717587, 2025). "In the context of cancer, FABP7 has been implicated in metabolic reprogramming of breast cancer cells, where it promotes glycolysis and lipid droplet accumulation, supporting tumor growth and survival." (PMID 40612672, 2025). "In patients with Her2-positive breast cancer, high FABP7 expression is associated with lower survival rates and a higher incidence of brain metastases." (PMID 39125761, 2024). "High expression of FABP7 is associated with poor prognosis and a high incidence of brain metastasis in breast cancer patients." (PMID 33926551, 2021). "FABP7 knockdown increased the susceptibility to hypoxia and γ-irradiation, providing a potential therapeutic window for breast cancer." (PMID 32647572, 2020). "Another study by Zhang H and colleagues also suggested that the proteins FABP7 was associated with the basal phenotype in human breast cancer." (PMID 33292226, 2020). "HIF-1α activity has been linked to the upregulation of fatty acid binding protein 7 (FABP7), which is involved in fatty acid uptake, binds to unsaturated fatty acids, and contributes to breast cancer tumorigenesis." (PMID 33266219, 2020). "FABP7 expression in normal and breast tumor biopsies was associated with mammary gland differentiation and its overexpression in human breast cancer cells induced differentiation." (PMID 19014610, 2008). "FABP7 has also been associated with a number of cancers outside the brain, notably breast cancer." (PMID 37207357, 2023). "FABP7 has been associated with response to chemotherapy and may be a potential biomarker predicting responses of breast cancer to neoadjuvant chemotherapy." (PMID 35783014, 2022). "Overexpression of FABP7 inhibited the proliferation of TUHR14TKB cells, which is consistent with findings that FABP7 (referred to formerly in the studies cited here as the protein encoded by mammary-derived growth inhibitor-related gene) inhibits the proliferation of breast cancer cell lines." (PMID 28292269, 2017). "In brain metastasis of breast cancer, FABP7 mediates a glycolytic phenotype to adapt to the brain microenvironment." (PMID 40717587, 2025). "In breast cancer, FABP7 promotes the formation of an immunosuppressive microenvironment by regulating angiogenesis-related genes (VEGFA/P4HA1)." (PMID 40717587, 2025). "Patients with high FABP7 expression in breast cancer have poor responses to neoadjuvant chemotherapy (e.g., paclitaxel and anthracyclines), but its expression level can predict the efficacy of anti-angiogenic drugs (e.g., apatinib)." (PMID 40717587, 2025). "CircZFR acts as an onco-circRNA in breast cancer by modulating the miR-223/fatty acid-binding protein 7 (FABP7) axis and reducing miR-223 activity." (PMID 39125761, 2024). "When exploring the mechanism of circ_ZFR action, they found that circ_ZFR promoted breast cancer cell progression by regulating the miR-223-3p/FABP7 axis." (PMID 38408962, 2024). "FABP7 expression in brain was also found to be positively correlated with breast cancer brain metastases." (PMID 37207357, 2023). "FABP7 is required for HER2-positive breast cancer cell growth by up-regulating key metastatic genes and pathways." (PMID 37179822, 2023). "More recent studies have demonstrated that fatty acid metabolism is essential for the brain metastasis of HER2+ breast cancer, possibly mediated by high levels of fatty acid binding protein 7 (FABP7), which supports formation of lipid storage." (PMID 36291900, 2022). "In conclusion, a thorough investigation of lipid metabolism-related genes was conducted for patients with breast cancer, and a prognostic signature encompassing two biomarkers (FABP7 and NDUFAB1) was discovered for the application of immunotherapy." (PMID 35562758, 2022).
breast cancer (continued). "Based on the prognostic value of FABP7 and NDUFAB1, LASSO Cox regression analysis was used to build a prognostic gene model that revealed that breast cancer patients with high risk scores had a lower overall survival rate than those with low risk scores." (PMID 35562758, 2022). "In cancers, FABP7 up-regulation and its diverse oncogenic functions have been found in glioma, breast cancer, melanoma, renal cell carcinoma, and colon cancer." (PMID 35269427, 2022). "FABP7 was suggested as a potential target for the treatment complications of HER2 in breast cancer patients." (PMID 36230586, 2022). "This notion is consistent with a large cohort of 1494 patients showing that breast cancers with cytoplasmic FABP7 expressions have shorter survival than those with nuclear expression." (PMID 35269427, 2022). "The findings of the prognostic analysis revealed that individuals with breast cancer who had FABP7 downregulation had a low chance of survival (P = 0.001) and upregulation of NDUFAB1 (P = 0.011)." (PMID 35562758, 2022). "Brain-predominant genes critical for the establishment of HER2 positive breast cancer brain metastases include a cytoskeletal protein βIII-tubulin (encoded by TUBB3 gene) and the fatty acid-binding protein 7 (encoded by FABP7 gene)." (PMID 34685621, 2021). "In our breast cohort, FABP7 was upregulated in cfRNA from patients with triple-negative breast cancer (TNBC) but downregulated in hormone receptor-positive (HR+) breast cancer." (PMID 33883548, 2021). "A previous study showed FABP7 as a potential target for the treatment of HER2 + breast cancer brain metastases." (PMID 34321580, 2021). "Through in vivo and in vitro experiments, researchers discovered that FABP7 can promote HER2 + breast cancer cells adaptation to the brain microenvironment by supporting the glycolytic phenotype and lipid droplet storage." (PMID 33926551, 2021). "FABP7 is known as a molecular factor affecting brain metastasis and survival/proliferation of breast cancer." (PMID 33816302, 2021). "Intriguingly, we recently found that the expression of FABP7 and other genes related to PUFA transport was associated with the enrichment of molecular pathways related to ICI in breast cancer tissues." (PMID 32647572, 2020). "Collectively, these results show that FABP7 knockdown upregulates UCP1 in the breast cancer cells presumably by inducing beige fat-like differentiation under normoxia." (PMID 32647572, 2020). "Previously, we demonstrated that a protein involved in fatty acid transport, fatty acid binding protein 7 (FABP7) experienced HIF1-dependent upregulation in hypoxic breast cancer cells." (PMID 32647572, 2020). "Generally, the expression of FABP7 was significantly lower in breast cancer than normal tissue samples." (PMID 33292226, 2020). "Anti-cancer drug sensitivity assay, real-time PCR, flow cytometry and western-blotting assays were used to investigate the function of FABP7 in breast cancer cells and examine the relevant mechanism." (PMID 33292226, 2020). "FABP7 knockdown in HCC1806 breast cancer cells significantly altered the expression of genes involved in the PD-1-related immune checkpoint pathway among the pathways related to immune responses." (PMID 31819188, 2020). "Future study on the predictive value and detail molecular mechanisms of FABP7 in contribution to chemosensitivity in breast cancer is warranted." (PMID 33292226, 2020). "The analysis in ONCOMINE database demonstrated that the mRNA level of FABP7 was significantly lower in breast cancer than normal-tissue samples across a series of datasets in multiple cancer types." (PMID 33292226, 2020). "Previously, we found that the knockdown of hypoxia-inducible fatty acid binding protein 7 (FABP7) increased reactive oxygen species (ROS) in breast cancer cells." (PMID 32647572, 2020).
breast cancer (continued). "The result agrees with previous study by Zhang H and colleagues, which indicated that the overexpression of FABP7 was correlated to a better survival outcome in patients with breast cancer." (PMID 33292226, 2020). "In summary, the findings from clinical samples suggested that FABP7 was a key molecule that contributed to the accumulation of PI(18:0/20:3), as well as the regulation of the immune checkpoint pathway in primary breast cancer." (PMID 31819188, 2020). "We investigated the association of tumor hypoxia, FABP7, and UCP1 across breast cancer patients using METABRIC and TCGA data sets." (PMID 32647572, 2020). "The FABP7 mRNA expression in breast cancer samples was lower than that in normal tissues (fold changes were − 21.383, p = 2.66E−6 or − 8.265, p = 3.37E−9)." (PMID 33292226, 2020). "We show that FABP7 knockdown upregulated the genes related to beige fat differentiation in a breast cancer cell line." (PMID 32647572, 2020). "FABP7's role as a tumor suppressor is suggested by the finding that its enforced overexpression inhibits proliferation of a breast cancer cell line." (PMID 21771320, 2011). "The role of FABP7 as a tumor suppressor in human mammary cells is suggested by the demonstration that its enforced overexpression inhibits breast cancer cell proliferation." (PMID 21771320, 2011). "FABP7 overexpression correlates with shorter survival in patients with glioblastoma and melanoma, but better outcomes in those with breast cancer." (PMID 21771320, 2011). "FABP7 was also shown to induce mammary differentiation and to mediate growth inhibition of breast cancer cells." (PMID 16623952, 2006). "A comparative analysis of breast cancer subtypes based on cancer cell heterogeneity reveals that FABP7 may act as a tumor suppressor, holding significant clinical implications for diagnosis, prognosis, and targeted therapy in breast cancer patients." (PMID 40717587, 2025). "Increased levels of fatty acid binding protein 7 (FABP7) are also seen in HER2-positive breast cancer BMs, and besides its role in metabolic reprogramming, FABP7 upregulates metastatic genes and pathways, such as Integrins-Src, MEK/ERK, Wnt/β-catenin, and vascular endothelial growth factor (VEGF)-A." (PMID 40076927, 2025). "Interestingly, FABP7 expression is frequently downregulated in breast cancer tissues, and it has been proposed as a potential biomarker for predicting response to neoadjuvant chemotherapy." (PMID 40612672, 2025). "In addition, increased levels of FABP7 have been associated with reduced survival and a higher incidence of brain metastases in patients with HER2+ breast cancer." (PMID 35783014, 2022). "Previous studies have revealed that FABP5 and FABP7 might regulate lipid quality and/or quantity to promote aggressiveness such as cell growth, invasiveness, survival, and inflammation in breast cancer cells." (PMID 36230586, 2022). "We observed that all 4 patients with breast cancer who had FABP7 detected in plasma had relatively high tumor fractions (>1%), consistent with the hypothesis that tumor shedding rate is correlated with DCB detection." (PMID 33883548, 2021). "FABP7 has also been shown to be related to different breast cancer subtypes." (PMID 34103512, 2021). "The mutually exclusive relationship between FABP7 and UCP1 expression suggested that FABP7 could negatively regulate UCP1-mediated thermogenesis in breast cancer." (PMID 32647572, 2020). "Moreover, the FABP7 expression was also lower in MDA-MB-231 breast cancer cells treated with doxorubicin than in the control group." (PMID 33292226, 2020). "Moreover, the highest FABP7 expression was observed in basal-like subtypes of breast cancer, while the lowest expression of FABP7 was found in the luminal subtypes." (PMID 33292226, 2020).
breast cancer (continued). "Under pathophysiological condition, FABP7 has been shown to be strongly expressed in several malignant tumors, such as glioma, breast cancer, and malignant melanoma and the expression levels correlate with the rate of tumor proliferation, poor patient prognosis and survival." (PMID 32873991, 2020). "We observed that FABP7 knockdown induced UCP1-mediated thermogenesis in a breast cancer cell line." (PMID 32647572, 2020). "In the current study, we investigate whether FABP7 inhibition results in another metabolic outcome in breast cancer." (PMID 32647572, 2020). "An array of public databases, including ONCOMINE, cBioportal, Breast Cancer Gene Expression Miner v4.0, and the Kaplan Meir-plotter, etc., were used to evaluate the potential functions, related signaling pathway, as well as prognostic values of FABP7 in breast cancer." (PMID 33292226, 2020). "The role of FABP7 in inhibiting the proliferation of a breast cancer cell line suggests that it may act as a tumor suppressor." (PMID 28292269, 2017). "FABP7 may serve as a therapeutic target for HER2-positive breast cancer or other types." (PMID 37179822, 2023). "Therefore, we hypothesized that FABP7 could predict the drug sensitivity in breast cancer cells through regulating the cell cycle." (PMID 33292226, 2020). "Thus, FABP7-knockdown-induced UCP1 activated autonomous heat production in breast cancer cells." (PMID 32647572, 2020). "In addition, the analysis also revealed that PUFA trafficking conducted by multiple genes like FABP7 could contribute to PI remodelling in breast cancer." (PMID 31819188, 2020). "Therefore, we tested whether FABP7 knockdown could affect the differentiation status of breast cancer cells and UCP1-mediated thermogenesis." (PMID 32647572, 2020). "Hence, FABP7 might accelerate the cell cycle by suppressing the activity of p27kip1, thus promoting the proliferation of breast cancer cells." (PMID 33292226, 2020). "Furthermore, investigations of the organelle-specific roles of FABP7 demonstrated that increased nuclear, but not cytoplasmic, FABP7 is associated with increased proliferation, pleomorphism, and tumor stage in breast cancer suggesting that nuclear FABP7 drives a more aggressive phenotype." (PMID 25866768, 2015). "Among these pathways, the p-ERK and p-AKT signaling in breast cancer, the LRP6/GSK3β/β-catenin axis in NPC, and the cytosolic fatty-acid-binding protein 7 (FABP7)/PPARγ axis in malignant gliomas have been reported." (PMID 40001923, 2025). "For example, how FABP7 regulates the metabolic phenotype of GBM stem cells and how FABP4 affects the maintenance of breast cancer stem cells." (PMID 40717587, 2025). "In another example, fatty acid-binding protein 7 (FABP7), a brain-specific intracellular lipid-binding protein, promotes the metabolic reprogramming of metastatic HER2+ breast cancer cells." (PMID 39408656, 2024). "Another study on breast cancer IMD, had found that the fatty acid binding protein 7 (FABP7) supports cellular glycolytic phenotype and storage of lipid droplets." (PMID 39540151, 2024). "FABP7, a protein whose expression positively correlates with circZFR, crucially promotes EMT, migration, invasion, and proliferation of breast cancer cells." (PMID 39125761, 2024). "The circRNA zinc finger RNA binding protein (circ_ZFR) has been shown to competitively bind to miR-223-3p, thereby enhancing fatty acid binding protein 7 (FABP7) expression, and promoting the cell growth, migration, invasion, and EMT process in breast cancer." (PMID 36613528, 2022). "More interestingly, by immune cell infiltration analysis of the prognostic signature constructed by FABP7 and NADUFAB1, a more significant correlation with tumour immune cells in breast cancer was demonstrated." (PMID 35562758, 2022). "Prognosis analysis identified the prognostic value of FABP7(Fatty acid binding protein 7) and NDUFAB1(NADH:ubiquinone oxidoreductase subunit AB1) in breast cancer patients." (PMID 35562758, 2022).